ALDH1A3 (aldehyde dehydrogenase 1 family member A3)
Diseases named in the same sentence as ALDH1A3 in open-access papers (continued):
Sharing a sentence is not in itself a finding about the gene and the disease.
tumor (continued). "Future studies with ALDH1A3 and tPA‐plasmin axis link will/should investigate in the context of the complexity of the tumour ecological system." (PMID 37753740, 2024). "We also noted that ALDH1A3 upregulated TIMP metallopeptidase inhibitor 3 (TIMP3) in MDA‐MB‐231 cells, and TIMP3 was highly co‐expressed with ALDH1A3 in the TCGA Cell 2015 patient tumour dataset." (PMID 37753740, 2024). "In neoplasia, ALDH1A1 and ALDH1A3 isoforms have been implicated as tumor-promoting factors and universal biomarkers of cancer stem cells (CSCs), including GSCs." (PMID 39513909, 2024). "A groundbreaking study from Devalaraja and colleagues provided a unifying theory by showing that tumor-expressed ALDH1a3 generates retinoic acid as a paracrine factor to activate tumor-associated macrophages and suppress CD4 T cell activity." (PMID 39133222, 2024). "For the HCC1806 tumors, the ALDH1A3 knockdown tumors treated with 2DG had the fewest tumor-initiating cells (right)." (PMID 39251846, 2024). "For exosomes derived from TAM, lncMMPA can be transferred to HCC cells to stabilize ALDH1A3, activate the aerobic glucose degradation pathway, lead to metabolic reprogramming of the miR548/ALDH1A3 pathway, and promote tumor proliferation." (PMID 38633106, 2024). "In patient tumours, co‐expression of ALDH1A3 and tPA was strongly correlated and we noted a positive association with the TNBC subtype, higher grade tumours, and worse progression‐free survival." (PMID 37753740, 2024). "Specifically, in TNBC cells we find that ALDH1A3 can transcriptionally regulate PLAT, PLAU, and SERPINB2; however, considering both the cell line and patient tumour data, the strongest overall evidence was between ALDH1A3 and PLAT/tPA." (PMID 37753740, 2024). "Usually, increased ALDH1A3 expression in the tumor compared to that of the corresponding normal tissue indicates enhanced malignity or a worse prognosis." (PMID 39001459, 2024). "To investigate the role of ALDH1A1 and ALDH1A3 for tumor cell survival in the bloodstream and during the extravasation process in vivo, we employed the larval zebrafish (Danio rerio) model to xenograft human prostate cells." (PMID 38169509, 2024). "Functionally, ALDH1A3 promotes tumour growth, invasion and metastasis, and contributes to chemoresistance." (PMID 37753740, 2024). "We noted significant associations between high numbers of ALDH1A3+ and tPA+ cells and the TNBC subtype (non‐TNBC versus TNBC) and higher tumour grade (grade 1 and 2 versus grade 3)." (PMID 37753740, 2024). "USP9X depolyubiquitylation of ALDH1A3 effectively increases the half-life of ALDH1A3 in vitro and in vivo, helping the tumor maintain high levels of tumorigenic stem cells." (PMID 39001459, 2024). "Although inhibiting ALDH1A3 is almost always described as decreasing tumor growth, in the case of TNBC MDA-MB-468 cells, ALDH1A3 knockdown intriguingly increased the tumor growth; but the metastasis capacity of the cell line decreased upon ALDH1A3 reduction." (PMID 39251846, 2024). "In vivo experiments have evidenced that ALDH1A3 silencing and miR‐4524b‐5p overexpression significantly reduced tumor growth and GBM cells radioresistance." (PMID 37551838, 2023). "Analysis of xenografted tumours derived from ALDEFLUOR-positive cells also showed high ALDH1A3 expression." (PMID 36651035, 2023). "Then, we also found, compared with the control group, the expressions of EGFRvIII and ALDH1A3 detected by immunohistochemical staining were significantly increased in the GBM tumor tissue of a mouse model of orthotopic xenograft." (PMID 36980923, 2023). "Of note, the immunoreactivity of ALDH1A3 was exclusively detected in the tumor infiltrative region, where neo-angiogenesis was active." (PMID 37686698, 2023). "In summary, ALDH1A3 promotes tumor progression, likely via effects on proliferation, apoptosis, migration, invasion, and clonogenicity." (PMID 36672441, 2023).
tumor (continued). "Among the three isoforms, ALDH1A3 has been described to be overexpressed in different neoplasms, including pancreatic cancer, high-grade gliomas, and ovarian cancer, but is not expressed in the non-neoplastic cells." (PMID 37047661, 2023). "ALDH1A3 is overexpressed in CSCs, always characterized by higher self‐renewal and tumor‐initiating capacity as well as drug resistance and worse prognosis in patients." (PMID 36694633, 2023). "The highly methylated level between tumor and normal tissues were ALDH1A3, EFEMP1, SPARCL1, CPXM2 and EFEMP1." (PMID 37563710, 2023). "Of note, ALDH1A3 was dominantly detected in the endothelial cells of tumor vessels and in glomeruloid, a proliferative vasculature typically seen in GBM, in the infiltration zone where an active neo-angiogenesis appeared." (PMID 37686698, 2023). "In vitro analyses suggests that ALDH1A3’s effects on tumor growth and metastasis are multifactorial." (PMID 36672441, 2023). "More interestingly, we observed the expression of ALDH1A3 in the endothelial cells (ECs) of tumor vessels and glomeruloid bodies, a GBM-specific proliferating vascular structure, besides its expression in tumor cells and glial cells." (PMID 37686698, 2023). "Reports also suggest that ALDH1A3 imparts increased colony formation or clonogenicity, which measures the ability of a single cell to form a colony, an in vitro indicator of the tumor-initiating capacity required to form primary and secondary tumors." (PMID 36672441, 2023). "In the present study, miR‐4524b‐5p was identified as the upstream regulator of ALDH1A3 signaling, which affects tumor proliferation and radioresistance in GBM." (PMID 37551838, 2023). "The TUNEL assay indicated that transfection with si‐ALDH1A3 or exposure to radiation resulted in a higher level of cell death in the tumor area of immunocompromised mice." (PMID 37551838, 2023). "Animal models need to be established to further investigate and confirm the regulatory effect of ALDH1A3–Linc00284-miR-361-5p in the CRC tumor microenvironment in the future studies." (PMID 36275636, 2022). "This suggested that the impact of ALDH1A3 expression on metabolite levels and metabolism is more impactful the in vivo tumor microenvironment, where nutrients and oxygen are also more limited." (PMID 34989902, 2022). "In accordance, inhibition of ALDH1a3 enzymatic activity by chemical inhibition or genetic knockout protects tumor cells from RSL3-induced ferroptotic cell death." (PMID 36552781, 2022). "A contributing factor for why TNBC is an aggressive disease is the high aldehyde dehydrogenase 1A3 (ALDH1A3) levels present in the subtype, which promotes tumor progression and metastasis." (PMID 34989902, 2022). "Targeted high performance liquid chromatography-mass spectrometry (HPLC–MS) of MDA-MB-231 tumor samples metabolomics revealed a distinct metabolite profile upon ALDH1A3 expression." (PMID 34989902, 2022). "ALDH1A3 is overexpressed in CSCs characterized by a marked drug resistance and the capacity to promote self-renewal, clonogenic growth and tumor-initiating capacity." (PMID 35299840, 2022). "In accordance, PI3K/AKT signal pathway was reported to function momentously in various tumors to induce the resistance of CDK4/6 inhibitors or temozolomide and be involved in ALDH1A3-dependent tumor progression." (PMID 35831872, 2022). "Here, lncMMPA, a myeloid-specific lncRNA, is released via exosomes from TAMs to tumor cells to stabilize ALDH1A3 and augment proliferation and aerobic glycolysis in HCC cells." (PMID 35986343, 2022). "It is possible that a small number of circulating PDA tumor cells have infiltrated into the bone marrow and induced a modest elevation of the Nqo-1 and Aldh1a3 methylation in BMDMs in KPC mice." (PMID 34711804, 2021). "So far, ALDH1A3 has been found to be involved in the regulation of the biological characteristics of tumor cells, such as stemness, proliferation, invasion, metastasis, and drug resistance." (PMID 33419984, 2021).
tumor (continued). "In examining the capacity of ALDH1A3 knockdown to reverse tumor growth, we found that knockdown of ALDH1A3 attenuated the pro-oncogene effects of ARL4C overexpressed in GBM cells." (PMID 33403039, 2021). "We then compared the methylation levels of Nqo-1 and Aldh1a3 in tumor infiltrated immune cells including TAMs, CD4+T cells, and CD8+T cells to BMDMs from the same KPC mouse." (PMID 34711804, 2021). "We chose Aldh1a3 and Nqo-1, whose methylation sequences were the best defined, to be examined for tumor-induced methylation in macrophages by MSP." (PMID 34711804, 2021). "Here, we terminated the experiment on day 49 for the MDA-MB-231 tumors, noting a significant increase in tumor volume upon ALDH1A3 OE, and day 74 for the slower-growing MDA-MB-436 tumors." (PMID 33575432, 2021). "ALDH1A1 was expressed in six out of nine tumors; ALDH1A2 was also expressed in six out of nine tumor samples, and ALDH1A3 was present in only one out of nine tumors examined." (PMID 34572134, 2021). "The tumor suppressor miR-187 significantly and inversely correlated with ALDH1A3 and negatively regulated its expression in a set of PCa cell lines." (PMID 34572930, 2021). "Fifteen of 30 cases showed a positive of ALDH1A3 immunoreactivity which was predominantly observed in the tumor infiltrative area (TI)." (PMID 32680476, 2020). "Consistent with the isolation of breast CSCs, the ALDE+ had higher ALDH1A3 levels and greater tumor growth capacity." (PMID 31197235, 2020). "ALDH1A3’s tumor-promoting activities are in part mediated by its generation of retinoic acid and subsequent gene expression changes; however, it is unclear which are ALDH1A3’s key downstream oncogenic effectors." (PMID 31197235, 2020). "The results revealed that in two datasets ALDH1A3 was upregulated in PDAC tissues compared to the corresponding adjacent non-tumor tissues." (PMID 32612951, 2020). "Some glial-shaped cells and tumor cells were found double positive for ALDH1A3 and GFAP (arrows, respectively)." (PMID 32680476, 2020). "The result showed that the expression of HK2 was higher in ALDH1A3-positive PDAC tissues, and correlated positively with the expression of ALDH1A3 in human PDAC tumor tissues." (PMID 32612951, 2020). "Our clinical study results showed that high expression of ALDH1A3 was correlated positively with tumor size and distant metastasis, and predicted poor prognosis in PDAC." (PMID 32612951, 2020). "Given the co-expression of NRAD1 with CSC marker ALDH1A3 in the Aldefluorhigh cells and the role of ALDH1A3 in gene expression regulation and tumor progression, we wondered if NRAD1 is regulated by ALDH1A3." (PMID 31197235, 2020). "We observed ALDH1A3 expression in tumor cells (arrows), in outermost layer cells of some glomeruloid tufts (arrows), as well as in vessels (arrows)." (PMID 32680476, 2020). "ALDH1A3 expression enriched in tumor infiltrative region highlights its crucial role in tumor invasiveness and progression." (PMID 32680476, 2020). "When the analysis was restricted to the luminal ER+ tumours, high BMI1 expression was associated with low expression of ALDH1A1 (P = 0.025), ALDH1A3 (P = 0.026), CD133 (P = 0.038), CD44 (P = 0.0001), CD24 (P = 0.004) and SOX10 (0.0006)." (PMID 32524353, 2020). "According to our results showing significantly increased expression of ALDH1A3 in both resistant cell lines, we decided to further analyze expression of this isoform in tumor samples." (PMID 31443351, 2019). "Similar effects of KYA1797K on the specificities in the suppression of the expression of β-catenin and pan-RAS as well as CD44 and ALDH1A3 were confirmed by IHC analyses of the PDX tumor tissues." (PMID 30965636, 2019).
tumor (continued). "Treatment with ATRA replaced ALDH1A3 in inducing the same opposing tumor growth and metastasis effects, suggesting that ALDH1A3 exerted these effects through activation of RA signaling." (PMID 30733805, 2019). "ALDH1A3 had opposing effects in tumor xenografts, increasing tumor growth and metastasis of MDA-MB-231 and MDA-MB-435 cells but decreasing them in MDA-MB-468 cells." (PMID 30733805, 2019). "ALDH1A1 and ALDH1A3 regulate cellular function in both normal stem cells and tumor-initiating stem-like cells, promoting tumor growth and resistance to drugs and radiation." (PMID 30733805, 2019). "In order to verify the clinical significance of our findings, the expression of the ALDH1A3 was examined in tumor tissues from 216 patients before administration of systemic chemotherapy." (PMID 31443351, 2019). "Independent studies have demonstrated that silencing ALDH1A2 or ALDH1A3 reduced clonal expansion of tumor-initiating cells and tumorosphere formation." (PMID 31867574, 2019). "It is critical to note that there is thus far no definitive in vivo evidence documented for FZD6-, LGR5-, or ALDH1A3-positive Side populations in terms of tumor evolution or drug-response in NB." (PMID 31867574, 2019). "Most recently, isoform ALDH1A3 prominently emerges as cancer stem-like cells target in neoplasms of the lung, bile duct, melanoma, prostate, and breast cancer." (PMID 30538217, 2018). "Although numerous studies have classified both ALDH1A1 and ALDH1A3 as markers of CSCs derived from several distinct tumor types, the functional roles of these enzymes in CSCs have not been well-defined." (PMID 28423611, 2017). "Patients with co-expression of c-Met and ALDH1A3 at tumor stage III-IV showed poor clinical outcome." (PMID 28966724, 2017). "In our study, Kaplan-Meier analysis revealed that patients with high ALDH1A3 expression at tumor stage III-IV had poor outcome (p = 0.0049)." (PMID 28966724, 2017). "AldH1A3 (aldehyde dehydrogenase family 1, subfamily A3) activity has been used to identify stem-like cells within the tumor epithelial cells." (PMID 27152840, 2016). "Apart from its association with the presence of the tumor in IHC of FFPE slides, we were able to measure ALDH1A3 in urine samples, finding a positive association with tumor appearance." (PMID 25969992, 2015). "They found differential expression of ALDH1A3/ RA inducible genes that promote or suppress tumor growth in dependency of the DNA methylation state." (PMID 26460734, 2015). "Nevertheless, the association of ALDH1A3 expression with Gleason score provides evidence of an increase in ALDH1A3 expression with tumor staging." (PMID 25969992, 2015). "It indicated that the invasive abilities of the tumor cells were significantly suppressed by ALDH1A3 silencing." (PMID 26575197, 2015). "We found that ALDH activity in HNSCC cells can be attributed, at least in part, to the ALDH1A3 isoform and inhibition of the ALDH1A3 expression by small interfering RNA (siRNA) decreases tumor cell radioresistance." (PMID 26460734, 2015). "The expression dynamic of ALDH1A3 upon irradiation by either induction or selection of the ALDH1A3 positive population correlates to in vivo curability, suggesting that changes in protein expression during radiotherapy are indicative for tumor radioresistance." (PMID 26460734, 2015). "Our study also suggests that not only the marker expression prior treatment, but rather expression dynamics of ALDH1A3 upon therapy correlates with tumor radiosensitivity." (PMID 26460734, 2015). "The ALDH1A3 gene was expressed on average 1,308 fold higher in the tumor cell lines as compared to the normal derived hTERT-HPNE cells, and 23.5 fold higher in the tumor cell lines as compared to the average of the normal derived tissue samples." (PMID 24053169, 2013). "Importantly, these findings confirm prior genetic data that suggest ALDH1A3 suppresses anti-tumor CD4 T cells." (PMID 41210994, 2025).
tumor (continued). "Myriad studies have hypothesized that ALDH1A3 works in a tumor-intrinsic, growth-promoting role whose inhibition would prevent tumor growth and thus offer a cytotoxic therapeutic strategy." (PMID 41210994, 2025). "Finally, we show that ALDH1A3-produced atRA works in a paracrine immunoregulatory fashion to promote tumor tolerance through depletion of Th17 CD4 T cells and enhancement of Th2 CD4 T cells." (PMID 41210994, 2025). "Additionally, USP14 was preferentially expressed in cells positive for ALDH1A3 in GBM tumor samples." (PMID 39990235, 2025). "Furthermore, the potential for combining ALDH1A3 inhibition with existing immune checkpoint inhibition therapy or senescent cell purgants to improve tumor patient prognosis needs to be verified through further cell, animal, and clinical studies." (PMID 40227735, 2025). "To definitely prove that these ALDH1A3 inhibitors block paracrine secretion of atRA to suppress anti-tumor immunity, we established a co-culture model of mouse T cells and mouse myeloid cells that had been treated with tumor cell conditioned media." (PMID 41210994, 2025). "To validate that the compounds discovered could block ALDH1A3 activity in a relevant disease model, we sought to test a syngeneic tumor model whose in vivo tumor growth was shown to be dependent on ALDH1A3 production of atRA and resultant immune suppression." (PMID 41210994, 2025). "To determine whether SETD7 regulates ALDH1A3 expression in vivo, we analyzed xenograft tumor tissues using RT-qPCR, Western blotting, and IHC staining." (PMID 41203594, 2025). "Mechanistically, ALDH1A3 leads to drug resistance by detoxifying cytotoxic aldehydes that are generated during oxidative stress or chemotherapy, thereby protecting CSCs from apoptosis and enabling tumour recurrence." (PMID 40887554, 2025). "This suggests that ALDH1A3 may influence patients’ response to radiotherapy or immunotherapy by regulating immune cells in the tumor microenvironment." (PMID 40227735, 2025). "Together the patient tumour and cell line data prompted us to prioritize our investigation on the effects of ALDH1A3 on the plasminogen activation pathway and if this pathway contributes to ALDH1A3‐mediated invasion and metastasis in TNBC." (PMID 37753740, 2024). "It suggests that increased tumor growth upon ALDH1A3 knockdown in the MDA-MB-468 cells, could be connected to the increased glycolysis, which is needed for in vivo tumor growth." (PMID 39251846, 2024). "We then tested whether ALDH1A1 and ALDH1A3 regulate tumor cells homing to bone and bone marrow colonization in vivo." (PMID 38169509, 2024). "At the same time, Aldh1a3 knockdown cells exhibited a higher number of formed tumor nodules." (PMID 38169509, 2024). "However, the unexpected relationship of ALDH1A3 with the CD24−CD44+ cell population provides new information about the balance that exists between these two distinct tumor-promoting CSC populations." (PMID 39251846, 2024). "Taken together, the in vivo data suggests that ALDH1A3’s effects on tumor growth are reflected in the changes it induces in the CD24−CD44+ cell population and the overall tumor-initiating cell frequency, which are also susceptible to the glycolysis inhibitor 2DG." (PMID 39251846, 2024). "We analysed for possible correlations between tumour pathology parameters and progression‐free survival based on the percentage of positive ALDH1A3, tPA, uPA, and PAI‐2 cells, or the combination of ALDH1A3 with tPA or uPA, or ALDH1A3 combined with PAI‐2 negative cells." (PMID 37753740, 2024). "The mechanisms behind these alternate tumor growth effects of ALDH1A3 in at least MDA-MB-468 cells are unclear; however, considering the recent findings of the switch that can occur between the distinct breast CSC population, we wondered if there was a potential compensatory effect." (PMID 39251846, 2024).